IGF1 (insulin like growth factor 1)
Diseases named in the same sentence as IGF1 in open-access papers (continued):
Sharing a sentence is not in itself a finding about the gene and the disease.
acromegaly (continued). "Thus, in acromegaly, the final level of glycemia is dependent on the balance between the activities of GH and IGF-1." (PMID 26514337, 2015). "Forty-two percent of the obese acromegaly patients had high IGF-1 levels." (PMID 26078758, 2015). "Acromegaly is characterized by chronic hypersecretion of growth hormone (GH), which primarily originates from a GH-secreting pituitary adenoma and induces the synthesis of insulin-like growth factor 1 (IGF-1)." (PMID 25103549, 2015). "In line with Melmed’s and Rosario’s findings in man, the current study also shows that the measurement of total serum IGF-1 can be useful for the purpose of screening diabetic cats for acromegaly, given its positive predictive value of 95% at a cut-off of 1000 ng/ml." (PMID 26023776, 2015). "Her IGF-1 level had risen above the normal range, confirming acromegaly beyond doubt." (PMID 26514337, 2015). "Acromegaly is a disease of excessive growth hormone (GH) secretion and the primary aims of treatment are to control GH secretion or its effects on GH-sensitive tissues, most notably increased insulin-like growth factor-1 (IGF-1) secretion." (PMID 24272033, 2014). "In a 16-week, Phase II study of 60 patients with active acromegaly, biochemical control of GH and IGF-1 levels was achieved by 27 % of patients after 12 weeks of treatment with subcutaneous (sc) pasireotide, and 39 % of patients achieved significant (≥20 %) tumor volume reduction." (PMID 23529827, 2014). "Acromegaly is caused by a pituitary tumor that secretes GH and the disease is characterized by elevated plasma levels of GH and IGF-1 and their effects on bone mass and strength are not yet clearly defined." (PMID 25147565, 2014). "In acromegaly, GH and IGF-1 excess increases bone turnover and remodeling." (PMID 25147565, 2014). "Higher IGF-1 concentrations can be detected under physiologic conditions in the young and pathologically in patients with growth hormone secreting pituitary adenomas (acromegaly or gigantism), but these patients present with hyperglycemia." (PMID 24736741, 2014). "Pharmacological intervention in acromegaly is therefore aimed primarily at suppressing secretion of GH from the pituitary or blocking the actions of GH at it receptors, along with a secondary reduction in circulating IGF-1 levels." (PMID 24166706, 2014). "Acromegaly is characterized by excessively high GH and (immunoreactive) total IGF1 levels." (PMID 24692508, 2014). "APolish study in 220 treatment-naïve patients with acromegaly reported nosignificant differences in basal plasma GH, IGF1 or fasting insulin concentrationsbetween normoglycaemic patients and those with impairments in glucose tolerance, although the latter group of patients wassignificantly older." (PMID 24692509, 2014). "In this respect, it would be interesting to measure IGF1 bioactivity, total IGF1, and S-Klotho levels in a group of patients with acromegaly, in which total IGF1 levels remain high during treatment with somatostatin analogs despite improvement in clinical symptoms." (PMID 24692508, 2014). "Acromegaly is characterized by excessive secretion of growth hormone (GH), usually due to a pituitary tumor, and a subsequent increase in insulin-like growth factor-1 (IGF-1) release from the liver and other tissues." (PMID 24166706, 2014). "While our patient's acromegaly improved significantly with decline in GH and IGF1 levels when octreotide was switched to pasireotide, he continued to have intermittent hypercortisolaemia and his glycaemic control deteriorated significantly requiring a new anti-diabetic medication." (PMID 24616766, 2013). "This large variation among studies reporting results of radiosurgery for acromegaly may be attributed to differences in hormonal remission criteria (threshold of GH or IGF-1 levels), treatment plans (radiation dose), and length of followup time." (PMID 22518121, 2012).
acromegaly (continued). "The overall treatment goal in patients with acromegaly is to achieve normalization of age, and sex-specific serum IGF-1 levels, as this may reverse the increased mortality rate associated with this disease." (PMID 22518121, 2012). "Thus, she was started on pegvisomant treatment 13 months after the initial diagnosis of acromegaly, at a dosage of 10 mg/day delivered subcutaneously, which rapidly decreased her IGF-1 serum level (251.3 ng/mL after two months of treatment)." (PMID 22233881, 2012). "Therapeutic interventions should be orientated on those biochemical indices that indicate a safe GH/IGF-1 concentration, as data on complete remission or even cure of acromegaly are still highly controversial due to problems of assay technologies and standardisation." (PMID 22550484, 2012). "Whereas overexpression of IGF-1 may contribute to acromegaly, moderate increases in IGF-1 expression seem to be important for physiological hypertrophy of the heart." (PMID 23114500, 2012). "Dopamine agonists can control GH and/or IGF-1 levels in 15-40% of patients with acromegaly." (PMID 20478050, 2010). "PEG effectively reduces IGF-1 levels and improves signs and symptoms of acromegaly." (PMID 19814797, 2009). "Changes in its connectivity can affect motor coordination and emotional states, and these may be either directly or indirectly related to the core pathology of acromegaly, which involves the chronic neurotoxic effects of long‐term GH and IGF‐1 excess on subcortical structures." (PMID 41550023, 2026). "This narrative review aims to provide an overview of how nutrition modulates the GH/IGF-1 axis and to summarize current evidence on the effect of various macronutrients and dietary patterns on biochemical control and comorbidity management in patients with acromegaly." (PMID 41472889, 2026). "Serum insulin-like growth factor 1 concentration was 75.9 ng/mL (SI: 9.95 nmol/L) (reference range, 94-284 ng/mL [SI: 12.3-37.2 nmol/L]), and growth hormone suppressed to 0.49 ng/mL (SI: 0.49 μg/L) following an oral glucose tolerance test, excluding acromegaly." (PMID 42220602, 2026). "While elevated IGF-1 is a hallmark of acromegaly, it may also be elevated in non-pituitary conditions such as poorly controlled diabetes mellitus, hepatic dysfunction, or renourishment states." (PMID 40842744, 2025). "These alterations were more pronounced in patients with active disease compared to inactive acromegaly and healthy controls, indicating that chronic GH/IGF-1 excess promotes structural remodeling of the AVA–LV outflow tract complex and may impair valvulo-ventricular coupling." (PMID 41302934, 2025). "Importantly, serum IGF1 and GH have been shown to be incomplete predictors of HRQoL in acromegaly." (PMID 39959623, 2025). "Although OGTT was not performed due to hypoglycemia risk, the diagnosis of acromegaly was supported by sustained IGF-1 elevation, characteristic physical findings, a pituitary macroadenoma on MRI, and histopathological confirmation of GH secretion postoperatively." (PMID 40842744, 2025). "Therefore, GIPR+ somatotroph adenomas had higher baseline serum IGF-1 levels than GIPR- adenomas." (PMID 40421250, 2025). "However, GH and IGF-1 levels did influence MASLD development in acromegaly." (PMID 40725515, 2025). "Acromegaly may be regarded as a “model disease” since it accumulates mechanisms potentially relevant for implant integration: excess GH/IGF-1, chronic low-grade inflammation, enhanced oxidative stress, and persistent alterations in trabecular and cortical microarchitecture." (PMID 41295066, 2025). "This opinion may be based on the long diagnostic delay in acromegaly, which is one of the main determinants of adenoma overgrowth and excessive GH and IGF-1 levels, with no implications on potential response to treatment." (PMID 38809458, 2024). "Additionally, some patients may experience worsening symptoms of acromegaly and higher IGF-1 levels close to the date of their next injection." (PMID 39598481, 2024).
acromegaly (continued). "In case of ineffective control of acromegaly with fgSRLs, combination therapy with cabergoline did not meet the consensus as further therapeutic step for the panelists (statement 5.1), even if, recently, this combination showed a good IGF-1 normalization rate (30–58% of cases)." (PMID 38809458, 2024). "Among factors that could influence and predict the efficacy of pegvisomant therapy in controlling acromegaly, a central role of baseline IGF-1 values on the probability of achieving a biochemical control of acromegaly during the treatment with pegvisomant was identified, in a real-life setting." (PMID 38197875, 2024). "Medical treatment, could lower GH and IGF-1, and improve both comorbidities of acromegaly and QoL." (PMID 38965637, 2024). "The lower IGF-1 levels in females with acromegaly may be also the reason for better GLS values." (PMID 37223021, 2023). "In the whole acromegaly group, the data reveal that homozygous risk allele carriers (rs1421085 (CC), rs9930506 (GG), rs9939609 (AA)) as well as carriers of only one risk allele, have lower IGF-1 (IGF-1 x ULN) (rs1421085; p = 0.041; rs9930506; p = 0.056; rs9939609; p = 0.029)." (PMID 37446150, 2023). "Furthermore, acromegaly may induce IGF-1 resistance due to IGF-1R downregulation or desensitization in the setting of chronic exposure to IGF-1 and concomitant hyperinsulinemia." (PMID 36882643, 2023). "The clinical status of acromegaly can be assessed using SAGIT, a comprehensive clinician-reported outcome instrument that analyzes five key features of the disease: signs and symptoms (S), associated comorbidities (A), GH levels (G), IGF-1 levels (I), and the tumor profile (T)." (PMID 38137499, 2023). "Medial wall resection in acromegaly resulted in the highest potential for biochemical remission ever reported, with an average postoperative day 1 GH levels of 0.96 ug/L and surgical remission rates of 92% based on normalization of IGF-1 levels after surgery (mean = 15.56 months; range 3–30 months)." (PMID 35705579, 2022). "Acromegaly patients with systemically high GH and IGF-1 levels also have significantly higher incidence of PCa and risk of PCa-related mortality (HR = 1.33 and 1.44, respectively), suggesting that IGF-1 has a positive effect on PCa development and progression, even in humans." (PMID 35370981, 2022). "In addition, the vitamin D supplementation and the prescription of bone active drugs may improve the bone quality in acromegaly patients, in particular in those with active disease, together with the early normalization of GH and IGF-1 levels." (PMID 35922724, 2022). "The IGF-I suppression observed by the selective estrogen receptor modulators tamoxifen and raloxifen seems to correspond to those observed with oral estrogens: a randomized open-label study in 2018 reported that raloxifene could decrease serum IGF-1 level in acromegaly." (PMID 34173929, 2021). "However, if GH and IGF-1 remain uncontrolled in patients with acromegaly, systolic dysfunction and even heart failure may eventually occur, which will seriously affect the survival of patients." (PMID 33869029, 2021). "In addition, a meta-analysis showed that, cabergoline single-agent therapy normalizes IGF-I levels in one third of patients with acromegaly, while in resistant acromegaly IGF-1 normalization is achieved in about half of patients when cabergoline is added to SSAs." (PMID 33535394, 2021). "It has been already shown that an altered circadian BP profile in patients with active acromegaly (non-dipping profile) may be associated with higher GH and IGF-1 levels." (PMID 35116005, 2021). "On the one hand, the diagnosis of acromegaly has evolved over the years from overt clinical manifestations (as viewed in subjects with advanced disease, thus exhibiting unambiguous signs and symptoms) to a milder phenotype thanks to the widespread use of MRI and ultrasensitive GH or IGF-1 assays." (PMID 32840821, 2021).
acromegaly (continued). "However, according to a recent consensus statement on multidisciplinary management of acromegaly IGF-1 values up to 1.2–1.3× upper limit of normal (ULN) range may be considered sufficient for control of acromegaly." (PMID 33803429, 2021). "Acromegaly is most commonly caused by a growth hormone (GH)-secreting pituitary adenoma, whereas Cushing’s disease results from an adrenocorticotropic hormone (ACTH)-secreting pituitary adenoma, with consequent overproduction of insulin-like growth factor 1 (IGF-1) and cortisol, respectively." (PMID 34275099, 2021). "In the literature, cardiovascular diseases are generally evaluated in acromegaly patients with echocardiography, and many studies have concluded that having high levels of GH and IGF-1 does not increase the risk of developing LVH or other cardiovascular diseases." (PMID 32148485, 2020). "Although an independent effect of GH/IGF-1 excess on the vasculature has not been proven, the currently available evidence strongly suggests that both controlled as uncontrolled acromegaly is associated with microvascular damage and endothelial dysfunction, and also pro-inflammatory changes." (PMID 32458292, 2020). "Therefore, lowering of IGF-1 levels by acromegaly treatment may lead to reversal of these pro-inflammatory changes and—consequently—soft tissue swelling, and thereby impact on OSAS severity." (PMID 31612224, 2020). "In addition, Klotho might be a link between GH/IGF-1, inflammation and metabolic dysregulation in acromegaly, since Klotho impacts on all these components." (PMID 32458292, 2020). "Therefore, it is plausible to state that severe disease activity and higher levels of GH/IGF1 may have a detrimental influence on periodontal health in patients with acromegaly." (PMID 33154456, 2020). "However, we could wonder if GH and IGF-1 effects on soft tissues could participate in periodontal disease protection in acromegaly as 9/29 of our patients had a thick gingival biotype." (PMID 32738132, 2020). "The chronic cardiotoxic and remodeling effects of GH/IGF-1 overload results in concentric biventricular hypertrophic cardiomyopathy, which may lead to heart failure, especially in patients with insufficiently controlled acromegaly." (PMID 32458292, 2020). "Thus, it may also provide clinicians with another tool, apart from GH and IGF-1, to assess disease activity in acromegaly." (PMID 32333268, 2020). "Excess GH/IGF-1 in acromegaly may involve all these abnormalities." (PMID 31396153, 2019). "In addition, the effect of decreasing GH and IGF‐1 following treatment of cortical structures in acromegaly is less known; a reduction in cortical thickness could further compromise bone structural integrity." (PMID 31844828, 2019). "Furthermore, the IGF-1 level has a significant influence on thyroid volume and thyroid hormone levels in acromegaly, which indicates that postoperational endocrine levels are worth closely monitoring for a good acromegaly prognosis." (PMID 29593792, 2018). "The aim of this study was to quantitatively analyze the facial characteristics and facial changes in acromegaly before treatment, identify the differences and features between the genders, and explore the correlations between facial changes and the GH level, the IGF-1 level and disease duration." (PMID 30555420, 2018). "Current medical therapies available to treat acromegaly consist of somatostatin analogues (SSAs) and dopamine agonist (DA) medication, both of which act to suppress GH secretion from pituitary adenomas or remnant tissue and thus lead to reduced IGF-1 levels and reduced symptoms." (PMID 27458240, 2016). "However, particularly incipient disease clinical features in acromegaly might be mild; according to Endocrine Society guidelines, IGF-1 screening in each patient with confirmed pituitary mass is recommended." (PMID 26869991, 2016).
acromegaly (continued). "The recognition that acromegaly can be accompanied by apparently normal GH concentrations and dynamics, mild or absent clinical features and pituitary tumors that are too small to be detected by MRI, must contribute to this difficulty, and indicates the importance of IGF-1 measurement in diagnosis." (PMID 27279011, 2016). "However, to our knowledge, there is no study reporting an association between the presence of d3-GHR and elevated IGF-1 in individuals without acromegaly and not treated with GH." (PMID 27982199, 2016). "However, modifications of glucose homeostasis induced by somatostatin analogues may have an overall minor clinical impact in acromegaly despite their significant improvement of GH and IGF-1 control." (PMID 27279011, 2016). "Indeed, anastrozole was administered when the circulating levels of IGF-1 were high due to the interruption of pegvisomant treatment, while the shift to tamoxifen coincided with re-starting pegvisomant and the subsequent metabolic control of acromegaly." (PMID 25962899, 2015). "However IGF-1 levels in the acromegaly patients influenced pain scores on this measure." (PMID 26078758, 2015). "Although the mechanisms by which acromegaly results in an increased risk of cancer have not been fully clarified, in vitro studies demonstrated that GH and IGF-1 have a proliferative and anti-apoptotic effect on different cell lines, eventually leading to neoplastic evolution." (PMID 25962899, 2015). "Since colorectal polyps and cancers are considered to develop earlier due to the effects of increased GH and IGF-1 in acromegaly patients, it may be appropriate to perform a colonoscopy screening in acromegaly patients more frequently and earlier relative to the overall population." (PMID 25614729, 2014). "Acromegaly is a disorder which usually results from a pituitary adenoma and is manifested with the increased circulating levels of growth hormone (GH) and insulin-like factor type 1 (IGF-1) and is characterized by overdevelopment of the distal bones, soft tissue, and the internal organs." (PMID 25614729, 2014). "In addition, we studied whether S-Klotho levels are elevated in active acromegaly and whether a relationship exists between S-Klotho levels and IGF1." (PMID 24692508, 2014). "The value of measuring IGF1 bioactivity in active acromegaly is unknown." (PMID 24692508, 2014). "In addition, the mean percentage of IGF1 bioactivity over total IGF1 was 0.81% in the 15 subjects with active acromegaly indicating that the IGF1 KIRA assay provides information about the circulating IGF1 system that fundamentally differs from that obtained by IGF immunoassays." (PMID 24692508, 2014). "First, S-Klotho and IGF1 may both be independent markers for the severity of acromegaly." (PMID 24692508, 2014). "In addition, IGF1 bioactivity was also more strongly related to physical measures of QoL than total IGF1, suggesting that IGF1 bioactivity may better reflect physical limitations perceived in patients with active acromegaly." (PMID 24692508, 2014). "Interestingly, our finding that IGF1 bioactivity was within the reference range in a considerable number of patients with active acromegaly is in agreement with the results published in the 1970s and 1980s, which were obtained using classical IGF1 bioassays based on cartilage stimulation." (PMID 24692508, 2014). "The Consensus on Criteria for Cure of Acromegaly 2010 defined biochemical cure to be (at 6 weeks postoperative followup visit) a random GH measurement of 2.5 μg/liter or less, glucose-suppressed (nadir) GH less than 1.0 μg/liter, and a normal sex- and age-matched IGF-1 level." (PMID 22518121, 2012). "In selected patients with acromegaly, rosiglitazone therapy may decrease GH and IGF-1 levels." (PMID 21600024, 2011). "In acromegaly patients, GWW was positively correlated with age (r = 0.49, P = 0.009) and 1.5 × ULN IGF-1 (r = 0.47, P = 0.049) and negatively correlated with hypertension history (r = −0.46, P = 0.016)." (PMID 41488995, 2026).